MITF (melanocyte inducing transcription factor)
Diseases named in the same sentence as MITF in open-access papers (continued):
Sharing a sentence is not in itself a finding about the gene and the disease.
melanoma (continued). "Sc-RNA sq was used to study MITF-low state role in melanoma progression in zebrafish genetic models with low activity of Mitfa, proving that very low or absent MITF activity characterized a residual disease like therapy-resistant melanoma." (PMID 35713744, 2022). "From a comprehensive collection of melanoma cell lines, we observed that MITF-methylated cultures were subdivided in 2 distinct subtypes." (PMID 36040798, 2022). "Several reports identified an inverse correlation between transcript levels of AXL and the transcription factor MITF in a melanoma subset characterized by marked resistance to MAPKis." (PMID 35798875, 2022). "High and low MITF level/activity co-exist in melanoma tumors and the switch in MITF expression (high and low) is reversible and responsible for melanoma heterogeneity and plasticity." (PMID 35158973, 2022). "Here, we demonstrate that the antioxidant enzyme thioredoxin reductase-1 controls the stability and function of MITF, the master regulator of melanocytes and melanoma." (PMID 36291795, 2022). "A low level of IkB reveals an increased activity of NF-κB transcription factor as we have already found in acidic cells, while the parallel reduction of MITF identifies a switch of melanoma cells from a proliferative to an invasive phenotype." (PMID 36499700, 2022). "MITF has also been reported to be involved in melanoma phenotype switching, in that low levels of MITF promote a more invasive/less proliferative melanoma cell phenotype." (PMID 35693944, 2022). "The genes that carry a moderate melanoma risk include MC1R and MITF, whose protein products are involved in melanin synthesis." (PMID 35465855, 2022). "Microphthalmia-associated transcription factor (MITF) is strongly associated with regulation of proliferation, survival and senescence of melanoma cells." (PMID 35203723, 2022). "Significantly, BRN2 contributes to the melanocytic-lineage oncogenic factor (MITF)-mediated progress of melanoma." (PMID 36224606, 2022). "Other studies showed that SMARCA4 is critically required for an extensive number of MITF as well as MITF-targets that are pro-survival genes in melanoma and for melanoma survival in vitro." (PMID 35323214, 2022). "MITF is frequently expressed in melanoma and has a critical role in the formation and progression of this type of cancer." (PMID 36045272, 2022). "Taken together, our study highlights a new level of regulation between two major mediators of melanoma progression, MITF and the MAPK/ERK pathway, which appears more complex than previously anticipated." (PMID 35091687, 2022). "MITF activity is needed for melanocyte development, and deregulation of its activity is reported in melanoma." (PMID 36551682, 2022). "In this study, we identified SMILE as a negative regulator of MITF in α-MSH-induced melanogenesis in melanoma cells." (PMID 36499416, 2022). "SMARCD1 and SMARCD2 also co-immunoprecitated with MITF in melanoma cells; however, the role these paralogues play in regulating melanoma tumorigenicity is not known." (PMID 35323214, 2022). "Inflammatory signals produced by low MITF melanoma cells or by the microenvironment can induce de-differentiation and the consequent loss of melanocyte-specific surface antigens." (PMID 35682684, 2022). "Studies have demonstrated that androgen receptor (AR) is important in promoting the metastasis of melanoma by targeting MITF." (PMID 35452181, 2022). "Genome-wide epigenetic characterization of the 15 melanoma cell lines with MITF promoter hypermethylation using the Illumina EPIC arrays displayed that lack of SOX10 mRNA was associated with hypermethylation of the SOX10 promoter." (PMID 36040798, 2022). "This suggests a cooperative behavior between MITF+ and MITF– melanoma cells particularly occurring in vivo." (PMID 36040798, 2022). "Collectively, this evidence has shown that MITF is heterogeneously expressed in tumours, and the role of MITF in promoting melanoma heterogeneity cannot be disregarded." (PMID 35740696, 2022).
melanoma (continued). "Of note, despite of such a dramatic gene amplification, the protein levels of MITF itself are only marginally increased, suggesting a limiting role of direct MITF gene amplifications in melanoma metabolic rewiring." (PMID 35912100, 2022). "Considering that SIP suppressed MITF expression in B16F10 melanoma cells, we then investigated if β-catenin signaling is involved in this suppression." (PMID 36501075, 2022). "ZEB2 knockdown in mouse melanoma cell lines led to a decrease in MITF and its target genes and an increase in ZEB1, thereby leading to a more invasive phenotype." (PMID 35682684, 2022). "In contrast, SOX10+MITF– melanoma cells had acquired expression of several NC lineage genes as compared with differentiated melanocytes." (PMID 36040798, 2022). "IGF2BP1 stabilized MITF mRNA and increased its expression and its transcriptional activity in melanoma, which was mediated by counteracting the miR-340–mediated degradation of MITF mRNA." (PMID 35935853, 2022). "In melanoma cells, high levels of MITF activity promote cell proliferation and pigmentation, while lower levels promote an invasive phenotype." (PMID 35580127, 2022). "Perhaps a negative feedback loop exists between RAC1 and MITF, as the growth of differentiated melanomas critically depends on MITF and that deletion of MITF results in the rampant activation of Rho family GTPases40." (PMID 36271142, 2022). "The combination of paradox inhibitors with suppressors of MITF amplification have shown promise for treating resistant late-stage melanoma." (PMID 35954441, 2022). "Follow-up experiments suggested that ZEB2 and SNAI2 act as tumour suppressors but ZEB1 and TWIST1 facilitate BRAF signalling in melanoma transformation by downregulating MITF." (PMID 35740696, 2022). "We also observed that RAC1 signaling opposes the proliferative effect of MITF because RAC1P29S suppressed the growth of differentiated melanomas." (PMID 36271142, 2022). "The effect of MITF repression of these genes was found to be reversible when MITF was knocked down in melanoma cells, resulting in increased focal adhesion complexes and resistance to BRAF inhibitor treatment." (PMID 36119516, 2022). "SMILE acts as a coregulator that interacts with CREB to repress its transcriptional activity on the MITF promoter; thus, decreasing melanin production via the downregulation of melanogenic enzymes in mouse B16/F10 melanoma cells." (PMID 36499416, 2022). "Evidence suggests that STAT3 can suppress expression of MITF, which is one of the main factors driving melanoma proliferation and differentiation." (PMID 35903898, 2022). "We have previously found anticorrelation between MITF promoter methylation and expression in melanoma tumors and cell lines, highlighting the epigenetic involvement in the regulation of MITF." (PMID 36040798, 2022). "Subsequently, through the employment of RNA sequencing technology and a panel of biochemical assays, melanocytic-specific transcriptional factor MITF was identified to mediate the influence of Wnt/β-catenin signaling in melanoma cell ferroptosis." (PMID 36429010, 2022). "Since high or low MITF expressing cells very likely display distinctive metabolic features in an MITF-dependent manner, different phenotypic melanoma subsets are likely to respond differently to the same microenvironmental signals." (PMID 35912100, 2022). "Our analyses of dedifferentiated melanomas support 2 distinct phenotypes with similarities in MITF promoter methylation but differences in SOX10 mRNA levels and DNA methylation status." (PMID 36040798, 2022). "Given that SIP reduced MITF expression in B16F10 melanoma cells, we postulated that Wnt/β-catenin signaling was responsible for this suppression." (PMID 36501075, 2022).
melanoma (continued). "Over the recent years, substantial evidence has accumulated to indicate that MITF plays a broad role in coordinating melanocyte and melanoma biology beyond its function in promoting melanocyte cell identity and regulation of melanosomal genes." (PMID 35771179, 2022). "PGC1α also induces MITF transcription in melanocytes and in melanoma, giving rise to the possibility of a positive feedback loop." (PMID 35912100, 2022). "MITF-independent mechanisms by which SMARCA4 promotes melanoma survival and invasiveness have also been reported." (PMID 35323214, 2022). "miR-340 and miR-218 inhibit melanogenesis by negatively regulating MITF expression and thus play an inhibitory role in melanoma production." (PMID 36438898, 2022). "The phenotype switching in melanoma is marked with downregulation of MITF and upregulation of RTKs, such as AXL and EGFR." (PMID 35406721, 2022). "In B16 melanoma cells, melanin production and the protein levels of tyrosinase were suppressed by reducing MITF expression." (PMID 36422527, 2022). "During melanogenesis, α-melanocyte-stimulating hormone (α-MSH) induction of MITF was mediated by a decrease in SMILE expression in B16F10 mouse melanoma cells." (PMID 36499416, 2022). "Using high-MITF (SKMEL28) or low-MITF (A375) drug-naive BRAFV600E melanoma cell lines, we derived MAPKi-resistant cell models to evaluate the role of DUSP4 in this setting." (PMID 35580987, 2022). "Somatically, MITF gene fusions have been reported in RCC, while MITF amplification is common in melanoma and aberrant MITF transcription is responsible for the oncogenic transformation of clear cell sarcoma subtypes." (PMID 35842725, 2022). "Nevertheless, these data confirm work from several laboratories suggesting that MITF is a key regulator that dictates melanoma heterogeneity." (PMID 35771179, 2022). "As a specific transcription factor in melanoma cells, MITF is a key regulator and promoter of mitochondrial respiration." (PMID 36620597, 2022). "Fluorescent microscopic evaluation showed that the treatment of brassinin inhibited MITF translocation into the nucleus compared with α-MSH-only treated B16F10 melanoma cells." (PMID 36613338, 2022). "In melanomas, TPC2 activates MITF (microphthalmia-associated transcription factor) via a GSK3β phosphorylation pathway." (PMID 35959977, 2022). "In melanoma cells, DDX3X-mediated regulation of Microphthalmia-associated transcription factor (MITF) translation was shown to be important for the metastatic phenotype." (PMID 36393867, 2022). "MITF-positive cells can be found at the site of metastasis, confirming the ability of melanoma cells to switch to and from these transcriptional states." (PMID 35912100, 2022). "By qRT-PCR, we found that in vitro treatment of CQ increased MITF mRNA levels in human melanoma cell lines." (PMID 35847840, 2022). "The expression of MITF leads to the upregulation of PGC-1α, which promotes mitochondrial oxidative respiration and reduces its detrimental effects, which underlie melanoma’s recurrence and metastasis." (PMID 36620597, 2022). "Analysis of the gene expressions of 329 melanoma patients from TCGA database, yielded three-class GESs (“immune”, “keratin”, and “MITF-low”) with the poorest survival of patients with the “keratin” signature." (PMID 35884783, 2022). "Together these findings illuminate the mechanisms by which TFAP2 and MITF coordinately regulate differentiation of melanocytes and the phenotype of melanoma cells." (PMID 35580127, 2022). "The complexity of the issue is emphasized by the fact that MITF-low melanoma cells are more invasive, whereas high MITF makes melanoma cells more proliferative and differentiated." (PMID 35055021, 2022). "Significant evidence has emerged to demonstrate that MITF coordinates melanocyte and melanoma biology in ways more than just increasing melanocyte cell identity and melanosomal gene regulation." (PMID 36429010, 2022).
melanoma (continued). "In summary, MITF activity in melanoma cells–and thus the phenotypes of these cells–depends in part on the presence of transcription factors that give MITF access to specific regulatory elements." (PMID 35580127, 2022). "Remarkably, the level of MITF activity also determines the invasive, proliferative, or differentiated phenotype adopted by melanoma cells, which ultimately affects patient outcome." (PMID 35580127, 2022). "Conversely, BRN2 can promote melanoma invasion via repressing MITF expression by binding to the MITF promoter or through activation of Notch signalling, followed by activation of miR-222/221 promoter." (PMID 35740696, 2022). "Melanoma phenotype switching has been proposed to be responsible for melanoma heterogeneity, controlled by cell-autonomous and microenvironment factors that impinge on MITF and EMT-TF regulation, particularly on ZEB1/2 and SNAIL1/2." (PMID 35267510, 2022). "In this experiment, SEL-F2 treated with B16F10 melanoma cells showed a reduced MITF expression in a concentration-dependent manner." (PMID 35806473, 2022). "This pro-survival function carries over into melanoma, where MITF is a lineage addiction oncogene that is amplified in 10% of primary and more than 20% of metastatic melanoma tumors." (PMID 35323214, 2022). "Here instead, we chose to try to identify genes that are likely regulated by MITF based on correlations in both cell lines and in vivo, combined with ChIP‐seq data from melanoma." (PMID 35771179, 2022). "In the case of LO2 administration, decreased levels of MITF expression were demonstrated in B16F10 melanoma cells." (PMID 36613979, 2022). "The MITF pathway is dysregulated in approximately 15% of melanoma cases, and MITF amplification occurs in 10% of primary melanoma and 15% of metastatic diseases." (PMID 35565444, 2022). "Progression of skin melanoma and its dissemination to local or distant organs relies on phenotypic plasticity of melanoma cells, orchestrated by EMT-TFs and microphthalmia-associated TF (MITF)." (PMID 35267510, 2022). "Understanding how MITF activity is regulated represents a key question since its dynamic modulation is involved in the phenotypic plasticity of melanoma cells and their resistance to therapy." (PMID 35091687, 2022). "Mechanistically, the authors found that in both BRAF and NRAS mutated melanomas, MEK inhibition increases MITF expression, which, in turn, upregulates the expression of PGC-1α." (PMID 36077374, 2022). "In comparison, the SOX10+MITF– NCSC-like melanoma cell lines had acquired expression of other NC-derived lineage markers such as SOX2 (expressed in glial lineages), SOX5, and SOX8 (expressed in neural progenitors)." (PMID 36040798, 2022). "A genome-wide study in melanoma cells confirmed that SMARCA4 cooperates with MITF to remodel chromatin at pigmentation loci and other MITF-target genes." (PMID 35323214, 2022). "In several cell lines, ERK activation induced growth arrest via MITF degradation, a process unique to melanocytes and the melanoma system." (PMID 35197475, 2022). "Heterogeneous expression of PAX3 in melanoma also contributes to MITF regulation by increasing binding of BRN2 to the MITF promoter." (PMID 35740696, 2022). "Subsequently, the classic MITF rheostat model has been updated in view of such lineage cell states together with a new proposed nomenclature; however, these novel melanoma phenotypes remain to be formally established." (PMID 36040798, 2022). "As melanomas have an NC origin, we explored the differences between the 2 consensus groups of MITF-methylated melanomas using expression of genes involved in the NC." (PMID 36040798, 2022). "By investigating the role of ARAF in NRAS-driven mouse melanoma through mass spectrometry experiments followed by a functional siRNA-based screen, we unexpectedly identified MITF as a direct ARAF partner." (PMID 35091687, 2022).
melanoma (continued). "Herein, we report that Wnt/β-catenin signaling regulates ferroptosis and melanoma immunotherapy efficacy via the regulation of MITF." (PMID 36429010, 2022). "In more than 90% of melanomas, an lncRNA SAMMSON, which plays an oncogenic role in association with MITF, is present." (PMID 36614156, 2022). "We next examined the levels of DDR1 and DDR2 in a collection of melanoma cell lines and short‐term melanoma cultures in relation to the cell state differentiation markers MITF, SOX10, and AXL." (PMID 34957688, 2022). "The development of melanoma cell lines sheltering MITF amplification prevented subsequent RNAi-mediated of MITF or the establishment of dominant-negative MITF." (PMID 36551688, 2022). "To analyze this, we first assessed the proliferative capacity of each MITF-methylated melanoma subset in vitro." (PMID 36040798, 2022). "The basic concept in melanoma is that the proliferative and invasive states are defined, in part, by the high level/activity of MITF and low level/activity MITF, respectively." (PMID 35158973, 2022). "Melanoma cells with melanocytic phenotype display high MITF and PGC1α expression, increased mitochondrial energy metabolism, and ROS detoxification capacities that allow cells to cope with oxidative stress." (PMID 35406721, 2022). "The reciprocal antagonism between MITF and Wnt5A can also control the dynamic phenotype switching in melanoma cells." (PMID 35406721, 2022). "This idea is further perpetuated by various studies showing that CREB1 directly upregulates MITF expression in human melanocytes or melanoma cultures." (PMID 36268034, 2022). "Our results showed that ERU exerted an essential role in modulating the melanogenesis in the melanoma cells by inhibiting the melanin content and suppressing the expression of the MITF and TYR, which are the key factors that promote melanin synthesis." (PMID 36670903, 2022). "MITF can transcriptionally regulate the expression of BCL2 to enable melanoma cell survival, whereas the function of MITF in alternative novel cell modalities, such as ferroptosis, remains elusive." (PMID 36429010, 2022). "MITF can promote survival, differentiation, and proliferation, and suppress melanoma invasion and senescence." (PMID 35771179, 2022). "Tirosh and colleagues found that cancer associated fibroblasts (CAFs) expressed high levels of AXL in melanoma tumours that also expressed high AXL but apparent low levels of MITF, both markers of therapeutic resistance." (PMID 35740696, 2022). "Several genes have been identified as genetically altered drivers of melanoma tumorigenesis, such as NRAS, CDNK2A, MITF, PTEN, KIT, GNAQ, GNA11 or CTNNB1, but most (60%) melanomas have BRAF gene mutations." (PMID 35326682, 2022). "A significant correlation between MITF and RagD gene expression levels is demonstrated by the analysis of microarray data of melanoma metastatic patients and melanoma cell lines." (PMID 35563798, 2022). "For instance, melanoma cell invasion and migration are provoked as a result of miR-182 upregulation which is triggered by the downregulation of both expressions of MITF and FOXO3." (PMID 36224606, 2022). "It has to be emphasized that the KIT receptor signaling pathway, containing NRAS and BRAF, is the dominating pathway in melanocytes (and evidently in melanoma), and it is responsible for activating the melanocyte-specific transcription factor MITF." (PMID 35628196, 2022). "On the other hand, less differentiated melanoma cells have low MITF and PGC1α expression, are more glycolytic, and exhibit high ROS production." (PMID 35406721, 2022). "By contrast, in melanomas, the microenvironment within tumors which is known to affect MITF activity, is complex and varies within and between tumors." (PMID 35771179, 2022). "The persister cell states in our zebrafish models share conserved mechanisms with human melanoma cells depleted for MITF or following BRAF inhibitor drug treatment." (PMID 35929478, 2022).